VDR (vitamin D receptor)
Diseases named in the same sentence as VDR in open-access papers (continued):
Sharing a sentence is not in itself a finding about the gene and the disease.
Obesity (continued). "Genetic studies have provided an opportunity to determine which proteins link vitamin D to obesity pathology, including the vitamin D receptor, toll-like receptors, the renin-angiotensin system, apolipoprotein E, vascular endothelial growth factor, and poly (ADP-ribose) polymerase-1." (PMID 23800102, 2013). "Due to the lack of gene expression data of VDR in our study, we cannot conclude whether VDR mRNA expression is upregulated or downregulated in serum in those with obesity and how it relates to the downregulation of serum VDR protein level in obesity." (PMID 41264635, 2025). "In this review, we summarize the current understanding of the VD/VDR axis in adipose tissue biology, from molecular pathways controlling lipid turnover and immune responses to experimental and clinical evidence linking vitamin D status with obesity-related complications." (PMID 41226298, 2025). "However, some studies have not observed significant relationships between the VDR BsmI variant and obesity-related parameters." (PMID 39045947, 2024). "VDR-deficient mice exhibited a systemic lack of VDR, leading to a decrease in adipose tissue mass, an elevation in overall energy expenditure, and an improved resistance to high-fat-diet-induced obesity." (PMID 39684239, 2024). "Hence, the miR-122/VDR/SREBF1 axis might be upregulated by Exo-AT, promoting lipogenesis and speeding the development and progression of obesity, since miR-122 contributes to adipogenesis by inhibiting VDR and activating the SREBF1 signaling pathway." (PMID 38003013, 2023). "To illustrate, in fat cells (adipocytes), vitamin D or its analog binds to VDR proteins and acts as a regulator agent in adipocytes’ differentiation and metabolism, and, consequently, alterations in this binding might influence the context of obesity." (PMID 36839157, 2023). "Despite the contradictory results regarding the expression changes of VDR during bleomycin-induced lung fibrosis, previous studies have shown that vitamin D treatment attenuates fibrotic changes in lung fibrosis models induced by obesity, bleomycin and paraquat, which is consistent with our study." (PMID 37627629, 2023). "Differential VDR expression in visceral AT may also influence lipid storage and adipocytes enlargement though the transcriptional regulation of angiopoietin-like protein 4 and lipoprotein lipase, which in turn result in liver impairment in obesity." (PMID 33126575, 2020). "Future functional studies of VDR gene, well-designed clinical trials with larger sample size and longer intervention periods and comprehensive assessment of other candidate gene involved in obesity and vitamin D metabolism may validate our findings." (PMID 31395070, 2019). "Other examples of nsSNPs reported to be associated with obesity included leptin (LEPR) rs1805094 (Lys656Asn), beta-2 adrenergic receptor (ADRB2) rs1042714 (Glu27Gln), beta-3 adrenergic receptor (ADRB3) rs4994 (Trp64Arg), and vitamin D receptor (VDR) rs2228570 (Met1Thr)." (PMID 29755414, 2018). "Therefore, inherited polymorphisms affecting VDR can be hypothesized to affect IGF signaling and, in turn, growth, obesity, and obesity-related diseases." (PMID 29112142, 2017). "It has been demonstrated that the intracellular concentrations of 1,25(OH)2D3 can play an important role in either promoting or inhibiting adipogenesis (which may be a target for modulation in the treatment of obesity) via the VDR and transcriptional pathways that it targets." (PMID 29112142, 2017). "Therefore, further research on the effect of VD3/VDR on obesity is needed." (PMID 27473111, 2016). "Gender differences were also noticed in our previous studies on VDR regulation of the virome and high-fat diet (HFD) obesity." (PMID 38248835, 2024). "It is imperative to further explore the role of the 1,25(OH)2D3/VDR-UCPs pathway system in the regulation of BAT development and function in obesity." (PMID 38004226, 2023).
Obesity (continued). "In an animal study, VDR knockout C57BL6 mice resulted in UCP-1 expression and protection from diet-induced obesity, which means disrupted expression of VDR results in a compensatory increase in UCP-1 expression." (PMID 36771240, 2023). "Inclusively, VDR expression may underlie the various effects of 25(OH)D and provide a mechanistic basis for the association between VDD and diseases that are related to obesity, in which it has been suggested that the low-grade inflammation in obesity may be linked to VDD." (PMID 35276762, 2022). "To further analyze the effect of obesity on the function of vitamin D, we analyzed the effect of HFD on VDR tissue expression." (PMID 33210060, 2020). "We have demonstrated the role of nuclear receptors (e.g., VDR and FXR) in regulating host physiology and microbial metabolites in health and obesity." (PMID 32355205, 2020). "In this study, we aimed to evaluate if obesity influences the expression of genes crucial for VD activation (CYP27B1), inactivation (CYP24A1) and action (VDR) in different adipose tissues depots." (PMID 31652924, 2019). "Obesity indexes including BMI, WC, BFP and triceps skinfold thickness were used to evaluate the relationship to the VDR SNPs." (PMID 30975133, 2019). "Thus, a gut-liver axis mediated by VDR may play a novel role in obesity and metabolic diseases." (PMID 30828578, 2018). "The multiple regression analysis was applied to examine the relationship between obesity and testosterone, HOMA-IR levels, vitamin D levels of follicular fluid, and VDR gene expression on gramulosa cells." (PMID 28670428, 2017). "The present study revealed that the incidence of PCOS was associated with lower vitamin D levels of follicular fluid and decreased level of VDR gene expression in granulosa cells, which was more dominant in the PCOS patients with obesity." (PMID 28670428, 2017). "Established VDR target genes such as PPARD and PPARGC1A, which are involved in protection against an adverse metabolic phenotype (obesity, insulin resistance), were positively correlated with serum 25OHD3 in this study." (PMID 28199350, 2017). "When a “disease threshold” is reached, in either obesity or cancer, PPARG and VDR expression, respectively, diminishes." (PMID 27579030, 2016). "Plausible mechanisms through which vitamin D might contribute to obesity include parathyroid hormone (PTH) and vitamin D receptor (VDR)." (PMID 40077674, 2025). "VDR mRNA expression was higher in visceral and subcutaneous adipose tissues in those with morbidity obesity compared to non-obese individuals." (PMID 41264635, 2025). "Additionally, SREBF1 interacts with other genes and metabolic pathways, such as promoting adipogenesis through the regulation of the VDR/SREBF1 axis, consequently influencing the progression of obesity." (PMID 40702573, 2025). "This is evidenced by the observation that VDRKO mice are resistant to diet-induced obesity due to increased expression of Ucp1, 2, and 3, as well as stimulated fatty acid oxidation in both WAT and BAT, and overexpression of VDR in adipocytes reduces thermogenesis in WAT and BAT, leading to obesity." (PMID 38928386, 2024). "miR-122 is enriched in adipose tissue–derived exosomes; it can target VDR and interact with the BS1 region of the sterol regulatory element-binding transcription factor 1 (SREBF1) promoter to suppress VDR and SREBF1 expression, thus leading to the pathogenesis of obesity." (PMID 36864020, 2023). "Obesity-related pathophysiologic factors, such as impaired vitamin D receptor sensitivity, are not ruled out and further mechanistic research is warranted." (PMID 36648947, 2023). "It does not have any agonist or antagonist activity towards FXR and VDR, but it suppresses lipogenesis and has potential in cholangitis and obesity treatment." (PMID 36431930, 2022). "The two SNPs (rs2853564- VDR, rs11023374- CYP2R1) identified in our work have not previously been linked to obesity phenotypes." (PMID 32534577, 2020).
Obesity (continued). "Interestingly, obesity induced by HFD modestly, but significantly repressed VDR expression by 26% and 32% in the testis and the ovary, respectively." (PMID 33210060, 2020). "Indeed, several studies demonstrated that vitamin D/VDR axis is involved in the modulation of gut microbiota, which in turn impacts on the development of MAFLD in obesity." (PMID 33126575, 2020). "Recently published studies show that gene modification of the vitamin D receptor (VDR) regulates fatty acid oxidation, energy metabolism and browning of white adipose tissue in part through UCP1 expression, demonstrating regulation of vitamin D in obesity." (PMID 28353634, 2017). "The immune system and vitamin D receptor (VDR) are only two of the suggested mechanisms for a link between vitamin D and cancer which may also be connected to obesity." (PMID 25255691, 2014). "Indeed, vitamin D receptor (VDR) knockout mice exhibited a lean phenotype and resistance to diet-induced obesity." (PMID 19500359, 2009). "Additionally, 1,25(OH)2D3 increases VDR gene expression in adipose tissue from subjects with obesity but not from lean subjects." (PMID 35893929, 2022). "Few previous studies have examined VDR SNP haplotypes as predictors of obesity and metabolic outcomes; however, their results may not be fully comparable with our findings due to the different VDR SNPs haplotypes investigated in these studies." (PMID 31395070, 2019). "Further, apparent alterations in white adipose metabolism in the adipose VDR overexpressors could be secondary to the obesity itself, and are difficult to evaluate without data on adipocyte size." (PMID 23272223, 2012). "Furthermore, the nongenomic pathway mediated by VDR may represent a crucial target for the development of obesity treatment interventions." (PMID 39092232, 2024). "In VDR-knockout mouse models, the absence of VDR showed substantial protective effects against high-fat diet-induced adipose tissue accumulation, whereas in another knock-in model, mice with overexpressed human VDR in adipose tissue developed obesity even under a standard diet." (PMID 36895943, 2023). "Nevertheless, without considering both VDR genotypes, vitamin D intake and circulating 25(OH) D data simultaneously, we could not determine the complex interplay between genetic variation in the VDR gen, and vitamin D with obesity or metabolic syndrome." (PMID 31395070, 2019). "Thus, the crosstalk between intestinal VDR signaling and gut microbiota may hold the key for how VDR signaling in non-adipose tissues can contribute to obesity and metabolic syndrome." (PMID 30828578, 2018).
osteoporosis (138 papers, 2006 to 2026). A condition of reduced bone mass, with decreased cortical thickness and a decrease in the number and size of the trabeculae of cancellous bone (but normal chemical composition), resulting in increased fracture incidence. "The obtained results complement studies on the association of VDR gene polymorphisms with the risk of osteopenia and osteoporosis in Polish women." (PMID 39859195, 2025). "Polymorphisms in the VDR gene, including FokI (rs2228570), BsmI (rs1544410) and TaqI (rs731236), have been extensively investigated for their associations with osteoporosis risk and BMD." (PMID 40831018, 2025). "Populations such as those in the Middle East and Iran are particularly prone to vitamin D deficiency, which, in conjunction with VDR polymorphisms, exacerbates osteoporosis risk." (PMID 40831018, 2025). "The correlation of VDR gene polymorphisms with the development of civilization diseases, including osteoporosis, has been confirmed by several studies." (PMID 40149488, 2025). "The VDR gene has been identified as a key regulator of bone strength and metabolism, with its polymorphisms significantly implicated in osteoporosis risk." (PMID 40831018, 2025). "The ApaI (rs7312366 C>A) VDR polymorphism is reported to be associated with osteoporosis in postmenopausal women, with the polymorphism potentially influencing VDR function and consequently calcium metabolism and bone health." (PMID 39982362, 2025). "VDR gene polymorphisms, particularly BsmI (rs1544410), ApaI (rs17879735) and TaqI (rs731236), were analysed in postmenopausal Polish women with osteoporosis to assess their association with BMD and fracture risk." (PMID 40831018, 2025). "Meta‐analyses have further reinforced ethnic variability in the association of VDR polymorphisms with osteoporosis." (PMID 40831018, 2025). "The aim of our study was to examine the influence of VDR rs1544410 (G>A) and rs11568820 (G>A) polymorphisms on the risk of osteoporosis in Polish postmenopausal women." (PMID 39859195, 2025). "An interesting result was obtained in the association analysis of VDR alleles and genotypes with densitometric results for women with osteoporosis." (PMID 39859195, 2025). "Many studies have been conducted showing the correlation of VDR gene polymorphisms with the development of various diseases, including osteoporosis." (PMID 39859195, 2025). "Many previous studies have investigated the association between VDR polymorphisms and osteoporosis risk." (PMID 39859195, 2025). "Recently, the meta‐analysis evaluated the association of four VDR polymorphisms (FokI, BsmI, ApaI and TaqI) with osteoporosis risk across 81 studies involving 19,268 participants, revealing significant findings influenced by ethnicity and genetic models." (PMID 40831018, 2025). "The heterozygous rs731236 variant of the VDR gene has also been shown to have a protective effect on the osteoporosis phenotype accompanied by increased BMI among women with osteoporosis." (PMID 39458556, 2024). "Secondly, the ApaI polymorphism (rs7975232) in the VDR gene is also associated with osteoporosis susceptibility." (PMID 39897963, 2024). "Polymorphisms of the vitamin D receptor (VDR) gene have been associated with osteoporosis in patients with autoimmune diseases." (PMID 38847864, 2024). "It focuses on how abnormalities in bone metabolism, autophagy, ferroptosis, and vitamin D receptor (VDR) gene polymorphisms contribute to osteoporosis in T2DM patients." (PMID 39897963, 2024). "Polymorphisms in the vitamin D receptor gene (such as TaqI and EcoRV) impact the metabolism of vitamin D and bone metabolism, thereby influencing the development of osteoporosis." (PMID 39897963, 2024). "VDR gene polymorphisms have also been found to be associated with the development of diabetes-related osteoporosis." (PMID 39897963, 2024). "Studies have shown that polymorphisms in the VDR gene significantly affect an individual’s susceptibility to osteoporosis." (PMID 39897963, 2024).
osteoporosis (continued). "The present study was designed to determine the association between the six well-known SNPs in the VDR gene and osteoporosis." (PMID 39072539, 2024). "Our findings not only elucidate the mechanisms by which an HFD induces BMSC senescence and associated osteoporosis but also offer new insights into treating HFD-induced osteoporosis by targeting the VDR-superoxide dismutase 2 (SOD2)-ROS axis." (PMID 38777841, 2024). "Specifically, the BsmI polymorphism of the VDR gene is implicated in the development of osteoporosis in RA patients." (PMID 38160213, 2024). "Regarding polymorphisms of the VDR gene in a Caucasian population, the meta-analysis in 2020 shows that FokI is associated with osteoporosis (ORdominant = 1.15; 95% CI = 0.96–1.38." (PMID 39125794, 2024). "Overall, our findings highlight the importance of the genetic polymorphism of VDR in the development of osteoporosis in the studied population." (PMID 39072539, 2024). "Dysregulation or alterations in VDR activity have been implicated in a variety of diseases, including osteoporosis, autoimmune disorders, and certain types of cancer." (PMID 38318147, 2024). "Existing studies have identified several gene polymorphisms associated with osteoporosis, such as VDR gene polymorphisms, which affect individual responses to vitamin D and, consequently, bone density and health." (PMID 39897963, 2024). "Extensive research has been carried out globally on the relationship between VDR gene polymorphisms, particularly ApaI, TaqI, and BsmI, and osteoporosis." (PMID 37957749, 2023). "Genetic variations in the VDR gene have been extensively studied in relation to osteoporosis susceptibility." (PMID 37957749, 2023). "The vitamin D receptor (VDR) gene polymorphisms ApaI, BsmI, TaqI and FokI are most frequently studied as potential factors predicting osteoporosis risk in middle-aged and older populations." (PMID 36834780, 2023). "More attention should be devoted to investigating the underlying mechanisms and causal causes of the positive associations observed between VDR polymorphisms and osteoporosis-related traits, as well as the efficacy of antiresorptive treatment." (PMID 36672934, 2023). "Dysregulation of the VD/VDR system has been linked to several bone pathologies, including osteoporosis." (PMID 37957749, 2023). "After applying DGS, we found that five gene locus polymorphisms in the Asian population were associated with osteoporosis: VDR FokI (rs2228570), IGF1 (rs2288377), IGF1 (rs35767), TGF β1 T869C (rs1800470), and ESR2 RsaI (rs1256049)." (PMID 35452412, 2022). "Genetic studies in older mice have also shed light on the molecular mechanisms underlying the important role of the calcitriol/VDR pathway in diseases of aging such as osteoporosis and cancer." (PMID 33553990, 2021). "The current study found a significant association between ApaI VDR genotypes and osteoporosis in Egyptian women." (PMID 34351532, 2021). "The association of VDR gene polymorphisms with the incidence of cancer, osteoporosis, and autoimmune thyroid disease has been confirmed in a meta-analysis." (PMID 34903261, 2021). "In conclusion, VDR gene variants (rs7975232, rs1544410, and rs731236) are associated with increased risk of osteoporosis and decreased BMD among Saudi Arabian post-menopausal women." (PMID 34698098, 2021). "Results herein indicate that rs7975232 and rs731236 variants in the VDR gene are significantly associated with an increased risk of osteoporosis." (PMID 34698098, 2021). "In total, 600 Saudi postmenopausal women (N = 300 osteoporosis; N = 300 control) were genotyped for VDR gene variants (rs7975232, rs1544410, rs731236) using TaqMan® SNP genotyping assays." (PMID 34698098, 2021). "Herein, the current study explores the association between VDR polymorphisms and susceptibility to osteoporosis in Saudi postmenopausal women." (PMID 34698098, 2021).